PTPN11 (protein tyrosine phosphatase non-receptor type 11)
Diseases named in the same sentence as PTPN11 in open-access papers (continued):
Sharing a sentence is not in itself a finding about the gene and the disease.
hypertrophic cardiomyopathy (27 papers, 2009 to 2025). A condition in which the myocardium is hypertrophied without an obvious cause. "NS-associated PTPN11 mutations typically present with pulmonic valve stenosis and to a much lesser extent hypertrophic cardiomyopathy (HCM)." (PMID 33689087, 2022). "Another two had hypertrophic cardiomyopathy, a feature which is negatively associated with PTPN11 mutations." (PMID 30784236, 2019). "Additionally, it is believed that PTPN11 mutations that result in a loss of function are correlated with hypertrophic cardiomyopathy." (PMID 35802774, 2022). "As expected, PTPN11 variants demonstrated a significant association with PVS and ASD (p < 0.05), while those involving RAF1 were preferentially associated with hypertrophic cardiomyopathy (HCM) (p < 0.0001)." (PMID 40332000, 2025). "Rapamycin has shown promise in reversing PTPN11 mutant hypertrophic cardiomyopathy in mouse models by inhibiting the mTOR pathway; however, its application in human subjects requires further clinical validation." (PMID 39105075, 2024). "Mutations in PTPN11 were most commonly associated with pulmonary valve stenosis (PVS), while RAF1 mutations were prevalent in patients with hypertrophic cardiomyopathy (HCM)." (PMID 39596663, 2024). "GSEA showed that PTPN11 was functionally involved in Asthma, Autoimmune thyroid disease, Cardiac muscle contraction, and Hypertrophic cardiomyopathy, indicating its direct connection with HCM as a critical biomarker." (PMID 38277535, 2024). "It is characterized most frequently by hypertrophic cardiomyopathy and is caused by mutations in the gene (PTPN11) that codes for the phosphatase SHP2." (PMID 21649940, 2011). "Loss-of-function variants in LZTR1 likely remove a critical checkpoint in this pathway, contributing to a spectrum of features including mild dysmorphisms and cardiac anomalies, although with a reduced prevalence of hypertrophic cardiomyopathy compared to RAF1 or PTPN11." (PMID 40332000, 2025). "Our GESA results indicated that a high expression of PTPN11 might activate myocardial contraction and hypertrophic cardiomyopathy." (PMID 38277535, 2024).
non-small cell lung carcinoma (27 papers, 2010 to 2026). A group of at least three distinct histological types of lung cancer, including non-small cell squamous cell carcinoma, adenocarcinoma, and large cell carcinoma. "Finally, we analyzed gene expression and drug response data collected from 21 non-small cell lung cancer (NSCLC) patients for PTPN11 and CD274 expression." (PMID 34437586, 2021). "IJMS is retracting the article titled "Protein Tyrosine Phosphatase Non-Receptor 11 (PTPN11/Shp2) as a Driver Oncogene and a Novel Therapeutic Target in Non-Small Cell Lung Cancer (NSCLC)" [...]." (PMID 42060675, 2026). "Similarly, the treatment of mice with an alternative allosteric PTPN11 inhibitor, SHP099, resulted in enhanced T cell recruitment to orthotopic non-small cell lung carcinoma (NSCLC) nodules." (PMID 38334623, 2024).
diabetes (24 papers, 2011 to 2025). "Among these are genes associated with insulin (MAX, NUCKS1, PIK3R1, PTPN11), diabetes (PIK3R1) and circadian-related processes (HNRNPU, BHLHE41)." (PMID 34745571, 2020). "SHP2 deregulation was shown to be involved in insulin resistance in type 2 diabetes mellitus (T2DM); accordingly, SHP2 inhibition or liver-specific PTPN11 deletion delayed IR endocytosis, enhanced insulin-activated AKT pathway and improved insulin sensitivity in mice." (PMID 41302504, 2025). "Although BVT 948 may be targeting several phosphatases, it exhibits greater efficacy against some PTPs, including PTP1B (PTPN1) and SHP-2 (PTPN11), that are drug targets for cancer, diabetes and obesity." (PMID 26061731, 2015).
metachondromatosis (24 papers, 2010 to 2025). Metachondromatosis (MC) is a rare disorder characterized by the presence of both multiple enchondromas and osteochondroma-like lesions. "Over the past decade, PTPN11 inactivation in chondrocytes was found to cause metachondromatosis, a rare disorder characterized by multiple enchondromas and osteochondroma-like lesions." (PMID 40379623, 2025). "More recently, postzygotic mosaicism of a specific PTPN11 variant, p.(Gln175His), has been linked to metachondromatosis." (PMID 35778969, 2022). "Loss-of-function mutations in PTPN11 results in development of metachondromatosis (MC), while Shp2 represses the proliferation of progenitor cell population in cartilage." (PMID 28085101, 2017). "Using linkage analysis and parallel sequencing of bar-coded DNAs from several families, mutations in Ptpn11 were identified as a cause of metachondromatosis, a rare tumor syndrome leading to cartilage tumors." (PMID 29085371, 2017). "Loss of PTPN11/SHP2 in mice or in human metachondromatosis (MC) patients causes benign cartilage tumors on the bone surface (exostoses) and within bones (enchondromas)." (PMID 24875294, 2014). "Recently, germline mutations of PTPN11 have also been identified in approximately 50% of cases of another bone disease, metachondromatosis (OMIM 156250), which is characterized by the development of benign exostotic and endosteal cartilagenous tumors." (PMID 24077964, 2013). "Inactivating mutations of PTPN11 have also been implicated in cases of metachondromatosis, which is characterized by the development of benign cartilaginous tumors." (PMID 24077964, 2013). "Recently, inactivating mutations in PTPN11 are reported in another enchondromatosis subtype called metachondromatosis in which multiple ECs are combined with osteochondroma-like lesions." (PMID 21235737, 2011). "Additionally, mutation in Ptpn11 has been shown to cause metachondromatosis, a rare syndrome leading to cartilage tumors." (PMID 29085371, 2017). "In contrast, metachondromatosis was recently reported in Ptpn11 conditional mice in which a cathepsin K (Ctsk)-promoter-driven Cre was used to disrupt Ptpn11 in Ctsk-expressing cells, which included a subpopulation of MSCs." (PMID 24077964, 2013). "This is consistent with our recent identification of a protein-truncating indel in the PTPN11 gene as responsible for metachondromatosis, a rare Mendelian disease affecting the skeleton." (PMID 20838461, 2010). "Similarly, Ptpn11 has also been proved to be a tumor suppressor in cartilage and involved in metachondromatosis by inducing hedgehog signaling." (PMID 25198338, 2014). "PTPN11 mutations in metachondromatosis include frame-shift, nonsense and splice-site mutations that are considered inactivating." (PMID 24077964, 2013). "Notably, although patients with metachondromatosis have one mutant copy and one normal copy of Ptpn11 in all cells, the normal copy is lost in cartilage cells that form tumors, reinforcing the critical tumor suppressor role of SHP-2 in cartilages." (PMID 29085371, 2017).
pancreatic cancer (24 papers, 2015 to 2026). "Pancreatic cancer risk increased via creating a binding site for miR-1231 upon the occurrence of SNP rs11655237 in LINC00673, via limiting degradation of protein tyrosine phosphatase non-receptor type 11 (PTPN11)." (PMID 37888204, 2023). "miR-1231 induces PTPN11 degradation and promotes pancreatic cancer growth." (PMID 32457613, 2020). "Then, PTPN11 was accumulated, and an oncogene IFNAR1 was upregulated, increasing the proliferation of pancreatic cancer cells." (PMID 37670967, 2023). "For example, LINC00673 enhances the interaction of PTPN11 with the ubiquitin ligase PRPF19 and promotes PTPN11 degradation through ubiquitination in pancreatic cancer." (PMID 36846713, 2023). "LINC00673 directly interacts with tyrosine phosphatase non-receptor type 11 (PTPN11) and functions as tumor suppressor in pancreatic cancer." (PMID 33219221, 2020).
Obesity (23 papers, 2011 to 2025). Accumulation of substantial excess body fat. "Thus, it is possible that the anti-obesity effects of chebulinic acid are caused by the inhibition of PTPN11 and PTPN9." (PMID 35055051, 2022). "However, based on the report that PTPN11 suppresses the adipogenesis of 3T3-L1 cells, we ruled out the possibility that the anti-obesity effects of chebulinic acid were due to PTPN11 inhibition." (PMID 35055051, 2022). "In the 12q24 area there are other genes that might be involved in the phenotype including THRAP2, TBX5 and PTPN11 for cardiac and great vessel anomalies; TBX5, CMKLR1, and TRPV4 for skeletal defects; PRKAB1, GPR109A, and GPR109B for increased hunger and obesity." (PMID 21457577, 2011).
myelodysplastic syndrome (21 papers, 2011 to 2025). A clonal hematopoietic disorder characterized by dysplasia and ineffective hematopoiesis in one or more of the hematopoietic cell lines. "Somatic gain-of-function mutations of PTPN11 are identified in patients with myelodysplastic syndrome (MDS), juvenile myelomonocytic leukemia, and de novo AML, especially in the FAB M4/M5 subtypes." (PMID 40566589, 2025). "It has been found that PTPN11 mutations are not limited to adult AML, but are also associated with a range of hematological malignancies, such as JMML, childhood AML, myelodysplastic syndromes, and acute B-lymphocytic leukemia." (PMID 38025540, 2023). "The gain of function mutations in PTPN11 are associated with 35% of human JMML, a disorder with excessive proliferation of myelomonocytic cells, and have been reported in a low percentage of myelodysplastic syndrome (MDS) and AML cases, and a few cases of solid tumors." (PMID 31277422, 2019).
lung adenocarcinoma (19 papers, 2010 to 2025). A carcinoma that arises from the lung and is characterized by the presence of malignant glandular epithelial cells. "To detect the correlation between KRAS and PTPN11, we screened the gene co‐expression of lung adenocarcinoma (LUAD) patients (n = 706) in TCGA database." (PMID 39992860, 2025).
colitis (18 papers, 2014 to 2025). Inflammation of the colon. "Specifically, PTPN11 CD4+ T cell deficient mice display enhanced TH1 immunity and aggravated colitis, but the deficiency inhibited the development of AOM-DSS colitis-associated carcinoma." (PMID 30429852, 2018). "In fact, an intestinal epithelial specific PTPN11 knockout mouse has been generated and develops severe colitis." (PMID 30429852, 2018). "It was therefore surprising that despite the increased inflammation observed in mice harboring a PTPN11 deficiency in CD4+ T cells, mice were protected against colitis associated cancer." (PMID 30429852, 2018). "In order to understand how inflammation contributes to CRC development, the present study focused on SHP-2, a tyrosine phosphatase encoded by PTPN11 gene in which polymorphisms have been shown to be markers of colitis susceptibility." (PMID 27582544, 2016). "PTPN11 was upregulated in both UC patients and a colitis model in mice." (PMID 39682729, 2024).
Insulin resistance (17 papers, 2013 to 2025). Increased resistance towards insulin, that is, diminished effectiveness of insulin in reducing blood glucose levels. "In addition to PTPN11 genetic variants, SHP2 overexpression has also been associated with glucose metabolism alteration and insulin resistance." (PMID 36140242, 2022). "Beyond rare diseases, PTPN11 has been reported as one of the 25 susceptibility genes for metabolic syndrome in humans, a common condition associated with cardiovascular diseases, metabolic disorders and insulin resistance, and inflammation." (PMID 36140242, 2022). "For example, MEK inhibitors ameliorate growth defect and lean phenotype in NS-associated PTPN11 mouse model but not the insulin resistance, which is driven by a direct effect of hyperactive SHP2 on macrophages (Ptpn11D61G/+ treated with U0126)." (PMID 37863846, 2024). "Deletion of PTPN11 has been shown to cause DCM, through loss of MAPK signaling pathway activation, while mutations of this gene have been associated with cardiac defects and insulin resistance." (PMID 38326862, 2024). "Several protein tyrosine phosphatases (PTPs), particularly PTPN1, PTPN2, PTPN6, PTPN9, PTPN11, PTPRS, and DUSP9, are involved in insulin resistance." (PMID 37374154, 2023). "Indeed, hepatocyte-specific Ptpn11 knock-out mice displayed better glucose tolerance and insulin sensitivity, which translated into protection from HFD-induced insulin resistance and T2D." (PMID 36140242, 2022).
ovarian carcinoma (17 papers, 2016 to 2025). A malignant neoplasm originating from the surface ovarian epithelium. "PTPN11 (SHP2), a critical node in receptor tyrosine kinase (RTK) signaling, is consistently upregulated in ovarian cancer and promotes tumor progression via the PI3K-AKT and ERK-MAPK pathways." (PMID 41181611, 2025). "Through integrated network analysis and clinical transcriptomic data, we identified five core targets (EGFR, JAK1, JAK2, PTPN11, and SRD5A1) that are differentially expressed in ovarian cancer tissues and serve as central nodes in TWP’s mechanism of action." (PMID 41181611, 2025). "Our investigation revealed that TWP’s efficacy is driven by its ability to modulate five core targets—EGFR, JAK1, JAK2, PTPN11, and SRD5A1—which our analysis showed to be dysregulated in clinical ovarian cancer datasets." (PMID 41181611, 2025). "PTPN18 is required for invasion in endometrial cancer cell lines and PTPN11/SHP2 enhances the invasion and metastasis of ovarian cancer cells." (PMID 33710332, 2021).
myeloma (16 papers, 2009 to 2025). "Our mutation profile (ARID1A, KMT2D, BCL7A, PTPN11, NUP214) and high CNV load converge with patterns reported across extramedullary/myeloma cohorts, notably MAPK pathway lesions and 1q amplifications." (PMID 41378284, 2025). "Importantly, IL-6 is one of the mediators of dexamethasone resistance in myeloma cells via protein tyrosine phosphatase, nonreceptor type 11 (PTPN11, also known as SHP2)." (PMID 34067236, 2021).
pulmonary stenosis (15 papers, 2016 to 2025). "The observed trend linking PTPN11 mutations to pulmonary stenosis, although statistically inconclusive due to sample size constraints, is biologically plausible and has been echoed in earlier genotype–phenotype studies." (PMID 41292581, 2025). "Sixty–seven of the patients with pathogenic variants in PTPN11 had congenital heart defects (84%), with pulmonary stenosis and secundum type atrial septal defect each accounting for 35.3% of the cardiac anomalies." (PMID 32164556, 2020). "Clinical features such as pulmonary stenosis (PS), short stature and thoracic deformities are more consistently associated with PTPN11 mutations than other clinical features." (PMID 32164556, 2020). "PTPN11 gene mutations have also been found in multiple lentigines (leopard) syndrome, also associated with pulmonary stenosis." (PMID 28228731, 2017). "PTPN11 gene variants were most common owing to being readily identifiable phenotypic findings, such as short stature (66.67%), down slanting palpebral fissures (41.67%), and pulmonary stenosis (41.67%) in many patients." (PMID 41292581, 2025). "Only two had pulmonary stenosis which is reported to be common for PTPN11 mutation carriers." (PMID 30784236, 2019). "A study of genotype-phenotype correlation reported that NS patients harboring PTPN11 mutations, especially a codon 308 mutation, had higher incidence of pulmonic stenosis than NS patients without PTPN11 mutations." (PMID 29084544, 2017). "In addition, pulmonary stenosis and ASD were most frequently seen in PTPN11 gene mutation-positive patients." (PMID 27125300, 2016). "A trend was observed for the association between PTPN11 and SOS1 variants and pulmonary stenosis, though not statistically significant due to the small cohort size." (PMID 41292581, 2025).
cardiac hypertrophy (14 papers, 2011 to 2025). "Previous studies have linked PTPN11 mutations with cardiac dysfunctions, including hypertrophy and heart failure, reinforcing its relevance in HCM." (PMID 41450821, 2025). "We observed that specific mutations in exon 13 of the PTPN11 gene were associated with early-onset cardiac hypertrophy and certain mutations such as the p.Q510E variant were associated with rapidly progressive HCM, in agreement with other studies." (PMID 30732632, 2019). "Loss-of-function mutations in PTPN11 gene, which encodes the Shp2, leads to congenital heart disease and adult-onset heart hypertrophy." (PMID 30086741, 2018). "In addition, PTPN11 mutation has also been demonstrated to be harmful to myocardial hypertrophy and cardiac fibrotic remodeling through crosstalking with NF-κB pathway and mTOR signaling." (PMID 36212153, 2022). "Rapamycin inhibition of mTOR activity can reverse cardiac hypertrophy in PTPN11-mutated LS mice." (PMID 31722741, 2019). "Moreover, patients with gain-of-function mutations of PTPN11 and attenuated mTOR pathway may also have cardiac hypertrophy, which cannot be explained by the animal studies." (PMID 31722741, 2019). "In addition, loss of function of Neurofibromatosis type I (NF1) and Shp2/PTPN11, two modulators of Alk associated Ras/Raf/ERK-signaling cause cardiac hypertrophy." (PMID 40382638, 2025). "In a PTPN11-mutant murine NSML model, treatment with rapamycin, an mTOR pathway inhibitor, ameliorated myocardial hypertrophy." (PMID 39202376, 2024).
Costello syndrome (14 papers, 2010 to 2024). "Among this group of disorders, craniosynostosis appears to be consistently associated with Noonan, CFC, and Costello syndromes with pathogenic variants most frequently reported in BRAF, HRAS, KRAS, and PTPN11." (PMID 37774117, 2024). "The remaining genes involved were RAF1 (three patients, all with Costello syndrome suspicion), RIT1 (two patients), BRAF (one patient), MAP2K1 (three patients), MAP2K2 (two patients), PTPN11 (two patients), SOS1 (one patient), and SHOC2 (three patients, two of them with Costello syndrome suspicion)." (PMID 37568403, 2023).
lupus (13 papers, 2018 to 2026). "Among them, we identified pathogenic or likely pathogenic variants in genes previously associated with monogenic lupus, including a novel C1QA variant as well as other lupus-associated genes (COPA, ADAR, TLR7, IKZF3, RELA, PTPN11, SERPING1)." (PMID 41930824, 2026). "Recently, a study demonstrated that the activity of PTPN11 on peripheral blood mononuclear cells (PBMCs) was increased in both lupus‐prone MRL/lpr mice and SLE patients." (PMID 33634995, 2021). "While, inhibiting the activity of PTPN11 could alleviate splenomegaly, suppress glomerulonephritis, and increase the life span of lupus mice." (PMID 33634995, 2021). "In this regard, the activity of SHP2 (the protein product of PTPN11) was shown to be increased in both lupus-prone mice and in human SLE patients." (PMID 32973676, 2020).